EGFR (epidermal growth factor receptor)
Diseases named in the same sentence as EGFR in open-access papers (continued):
Sharing a sentence is not in itself a finding about the gene and the disease.
bone metastasis (continued). "Among patients who were diagnosed with stage IV NSCLC from 2003 to 2012 in our institute, 63.9% of patients with mutant EGFR were detected to have bone metastasis, while 54.4% of patients with wild type EGFR were found to have bone involvement (p = 0.004)." (PMID 29113396, 2017). "Three of four patients (3/4, 75%) with bone metastasis progression continued EGFR TKI treatment with bone radiation therapy." (PMID 26172562, 2015). "Bone metastasis was present in 66.7% of patients with EGFR 21m and 46.7% of patients with EGFR 19m." (PMID 40004680, 2025). "The baseline clinical characteristics of EGFR‐mutated NSCLC patients with or without bone metastasis (BoM)." (PMID 38549499, 2024). "Notably, prolonged use of prior EGFR TKI, better responses to treatment, bone metastasis were closely associated with an increased likelihood of detecting T790M mutation." (PMID 39252953, 2024). "In addition, subgroup analysis revealed that patients harboring 19‐Del who received EGFR‐TKIs combined with radiotherapy (either for bone metastasis or thoracic radiotherapy) experienced a longer OS duration than those harboring 21‐L858R." (PMID 38659399, 2024). "Furthermore, patients with Stage IV LUAD and 19‐Del who received EGFR‐TKIs along with radiotherapy for bone metastasis achieved a longer OS duration than those with the 21‐L858R mutation (mOS: 34.7 vs. 25.1 months; 95% CI: 0.3915–0.8397; p = 0.0056)." (PMID 38659399, 2024). "Similarly, bone metastasis was associated with CEA levels while poor PS, brain, and bone metastases were associated with CYFRA21‐1 levels in EGFR‐positive patients." (PMID 38400801, 2024). "The baseline clinical characteristics of EGFR‐mutated NSCLC patients with bone metastasis (BoM) who received or did not receive denosumab." (PMID 38549499, 2024). "In this study, OBR developed in 82% of patients with EGFR-mutant NSCLC with bone metastasis." (PMID 37674153, 2023). "Hence, this study aimed to investigate the prevalence of OBR, the details of bone metastasis and OBR, and the association between OBR and clinical outcomes in patients with EGFR-mutant advanced NSCLC treated with osimertinib." (PMID 37674153, 2023). "Evidence suggests osimertinib has better CNS penetration than afatinib and may provide better clinical outcomes in patients with bone metastasis, therefore we recommend it over other EGFR TKIs in patients with CNS or bone involvement." (PMID 36765587, 2023). "Therefore, we believe that our nomogram can be used as an effective non-invasive tool to detect the EGFR mutation and subtypes in NSCLC patients with bone metastasis." (PMID 37143947, 2023). "P03 was a female patient with EGFR L858R-mutant advanced LUAD with bone metastasis." (PMID 36686783, 2022). "Noninvasive evaluation of EGFR mutation status and subtypes based on bone metastasis is of great clinical significance, yet it has not been well studied." (PMID 35964032, 2022). "The EGFR mutant bone metastasis had lower bmSUVmax (median 7.7 vs 9.7, p < 0.015)." (PMID 32742498, 2020). "In the multivariate analysis, five factors were recognized as the independent prognostic factors for OS including EGFR plasma and bone metastasis at baseline, treatment method, new metastasis site and cfDNA (P = 0.044, 0.012, 0.012, 0.003 and 0.004, respectively)." (PMID 30661185, 2019). "At the time of bone metastasis, 81% had multiple bone lesions and 63.7% had osteolytic lesions, which were not significantly different between patients with and without EGFR mutation (p = 0.116, p = 0.149; respectively)." (PMID 29113396, 2017). "In the multivariable analysis, prolonged PFS was independently associated with an ECOG PS of ≤2 (p = 0.006), common EGFR mutations (p < 0.001), no bone metastasis (p < 0.001), no liver metastasis (p = 0.005), and no pleural metastasis (p = 0.004)." (PMID 26894507, 2016).
bone metastasis (continued). "Bone metastasis and male sex are thought to be associated regardless of the presence/absence of EGFR gene mutations; however, further investigation of the tumor markers and pathological findings and the risk of bone and CNS metastases in postoperative EGFR‐positive NSCLC patients is needed." (PMID 39245880, 2024). "Furthermore, subgroup analysis highlighted a longer OS for the 19‐Del group compared to the 21‐L858R group, especially when EGFR‐TKIs were combined with bone metastasis or thoracic radiotherapy (mOS: 34.7 vs. 25.1 months and 51.0 vs. 29.6 months; p = 0.0056 and 0.0013, respectively)." (PMID 38659399, 2024). "Furthermore, patients with EGFR mutations and bone metastases appear to have better OS than those without EGFR mutations and bone metastasis." (PMID 36765587, 2023). "Age, sex, smoking history, ECOG-PS, pathological type, brain metastasis, liver metastasis, bone metastasis, lung metastasis, line of treatment, clinical stage, EGFR mutation and PD-L1 TPS in the study protocol groups were not statistically significantly different." (PMID 36569915, 2022). "However, the clinical efficacy of osimertinib in patients with NSCLC with other metastatic organs such as bone or liver remains unclear; although, patients with EGFR-mutant NSCLC have a higher frequency of bone metastasis than patients with EGFR-wild type." (PMID 35698083, 2022). "By incorporating EGFR, ERBB2, and ERBB3 expression in a decision tree model, four ERBB receptor status groups could be developed to segregate patients based on the risk of developing bone metastasis." (PMID 33918389, 2021). "In the univariable analysis, prolonged PFS was significantly associated with an ECOG PS of ≤2 (p < 0.001), common EGFR mutations (p < 0.001), no brain metastasis (p = 0.001), no bone metastasis (p < 0.001), no liver metastasis (p < 0.001), and no pleural metastasis (p = 0.007)." (PMID 26894507, 2016). "In particular, the progression of the disease can be delayed, and life quality can be consequently enhanced with the use of EGFR-TKI, representing a positive aspect of bone metastasis in OS patients." (PMID 41551443, 2026). "Global SHAP analysis showed that the most important input features in predicting bone metastasis were AJCC staging, the use of EGFR inhibitor, age, T‐staging, and lymphovascular invasion." (PMID 39556481, 2024). "During the inclusion period, 138 patients received osimertinib as first-line treatment for EGFR-mutant NSCLC, and 51 patients (37%) had bone metastasis." (PMID 37674153, 2023). "Before EGFR-TKI treatment, five patients showed metastasis in the lungs, two were diagnosed with brain metastasis, and one was diagnosed with bone metastasis." (PMID 33889543, 2021). "Their findings showed that performance status, line of chemotherapy, response to EGFR-TKI, and bone metastasis can effectively predict the 6-, 12- and 18-month PFS for NSCLC patients." (PMID 34805200, 2021). "This retrospective study was to explore the correlation of EGFR status and the usage of TKIs with the incidence of SREs in NSCLC patients with bone metastasis." (PMID 29113396, 2017). "Among patients who developed acquired EGFR amplification after first‐generation EGFR‐TKI treatment, 6.8% (4/59) developed liver metastasis, 18.6% (11/59) developed brain metastasis, and 35.6% (21/59) developed bone metastasis." (PMID 39741120, 2025). "Additionally, before third‐generation EGFR‐TKI treatment, 35.6% of patients in the EGFR amplification group had bone metastasis, 20.3% had brain metastasis, and 6.8% had liver metastasis." (PMID 39741120, 2025). "Univariate analysis showed that EGFR mutation was associated with pleural fluid CEA and serum CEA (P < 0.05), but not with gender, age, smoking history, bone metastasis, or brain metastasis (P > 0.05)." (PMID 37775991, 2024).
bone metastasis (continued). "Longer duration of initial EGFR TKI use (OR 1.792, ≥8 months vs. <8 months, p=0.004), better EGFR TKI responses (OR 1.611, complete or partial response vs. stable disease, p=0.006), presence of bone metastasis (OR 2.286, p<0.001) were correlated with higher T790M positivity." (PMID 39252953, 2024). "Our study showed that EGFR mutation was associated with pleural fluid CEA and serum CEA in univariate analysis, but not with gender, age, smoking history, bone metastasis, or cranial metastasis." (PMID 37775991, 2024). "Particularly, it is suggested that repeated rebiopsies may be valuable for patients with prolonged EGFR TKI usage, better responses to treatment, and bone metastasis." (PMID 39252953, 2024). "Compared with radiotherapy for brain or bone metastasis, the combination of EGFR‐TKIs and thoracic radiotherapy not only significantly improved mOS predictability but also increased the OS period in patients (36.6 vs. 30.7 vs. 31.7 months)." (PMID 38659399, 2024). "The increased incidence of OBR in patients with EGFR-mutant NSCLC with bone metastasis treated with osimertinib should not be confused with disease progression, and treatment decisions should be made carefully." (PMID 37674153, 2023). "Multifactorial analysis showed that bone metastasis was a significant independent negative predictor of OS in patients with mutant and wild‐type EGFR." (PMID 34799997, 2022). "On the other hand, there was no prognostic difference observed between NSCLC patients with bone metastases received EGFR-TKIs plus bisphosphonates and those without bone metastasis treated with EGFR-TKIs alone." (PMID 26624882, 2016). "However, the EGFR mutation (+) group did not: BMA (−) n = 11, median post-bone metastasis survival 24.1 months (95% CI: 7.0–N/A); BMA (+) n = 28, median post-bone metastasis survival 31.0 months (95% CI: 17.6–36.5) (p = 0.49)." (PMID 39851958, 2025). "A very recent real-world study comparing the efficacies of different EGFR-TKIs showed that osimertinib, a third-generation EGFR-TKI, was not superior over other TKIs in patients with liver metastasis, while it provided significant clinical benefits in patients with brain or bone metastasis." (PMID 36140210, 2022). "However, EGFR-Thr790Met was more frequent in male patients (66.7% vs. 33.3%), in patients without bone metastasis (88.9% vs. 11.1%) and in older patients (77.8% vs. 22.2%)." (PMID 35955661, 2022). "While EGFR plasma (P = 0.044) with bone metastasis at baseline (P = 0.012), new metastasis (P = 0.003), and high cfDNA concentration (P = 0.004) serve as the worse survival factors, surgery treatment helps to prolong OS in NSCLC treated with EGFR TKI (P = 0.012)." (PMID 30661185, 2019). "Treatment with an EGFR inhibitor may prolong survival following bone metastasis; however, interstitial pneumonia remains a serious side effect, and it has been reported EGFR inhibitors are less effective in patients without the EGFR gene." (PMID 25452785, 2015). "While the presence of bone metastasis at recurrence is reported as a poor prognostic factor in terms of both the PFS and OS in patients with advanced EGFR‐positive NSCLC, no reports are available on the prognostic impact of bone metastasis in EGFR‐positive NSCLC patients with PR." (PMID 39245880, 2024). "Based on the results that ALK‐positive patients were inclined to have brain and bone metastasis, we hypothesized that ALK‐positive patients tended to form distant metastasis through hematogenous spread, while both ALK‐ and EGFR‐negative patients tended to invade local region by lymphatic vessels." (PMID 28374971, 2017).
colitis (74 papers, 2010 to 2026). Inflammation of the colon. "Mice with a genetic deficiency of amphiregulin or amphiregulin receptor (EGFR) were found to be susceptible to DSS-induced colitis." (PMID 38376154, 2024). "EGFR activation also contributes to ameliorating chronic inflammation, limiting colitis-associated tumorigenesis." (PMID 35888995, 2022). "Berberine also exerts antiproliferative activity by participating in inflammatory response-driven epidermal growth factor receptor (EGFR) signaling pathway, thereby preventing the progression of colitis-associated CRC." (PMID 35046810, 2021). "In particular, myeloid EGFR is the pivotal trigger of harmful pro-inflammatory mediators in UC and colitis-associated cancers." (PMID 32461676, 2020). "LINGO2 deficiency basally elevates EGFR activity, susceptibility to colitis and resistance to helminth infection." (PMID 31562318, 2019). "Excessive basal EGFR activation in Lingo2 deficient mice increases disease severity during colitis and augments immunity against helminth infection." (PMID 31562318, 2019). "A major concern with EGFR-activating therapies in IBD is that they will increase the burden of colitis-associated cancer." (PMID 29904166, 2018). "Our prior findings showed genetic disruption of EGFR caused earlier onset and more-severe colitis in susceptible (i.e., Il10−/−) mice." (PMID 29904166, 2018). "To support the role of RHBDD1 in CRC and to substantiate the functional link between RHBDD1 and the EGFR signalling pathway, we performed confirmatory experiments in a murine model of colitis-associated CRC." (PMID 26300397, 2015). "Toll-like receptor 4 signalling activation seems to promote the development of colitis-associated cancer by mechanisms including enhanced Cox-2 expression and increased EGFR signalling." (PMID 20145615, 2010). "This aligns with recent findings that EGFR activation during acute bouts of colitis may reduce the long-term burden of colitis-associated cancer, emphasizing the complex and context-dependent role of these pathways." (PMID 41550766, 2026). "Inhibiting EGFR signaling inhibits recovery from colitis and associated CLDN2 upregulation." (PMID 37815870, 2023). "Importantly, ADAM17-mediated EGFR activation is essential for gut regeneration, and Adam17 and Egfr-deficient mice are more susceptible to colitis induced by oral administration of the sulfated polysaccharide dextran sodium sulfate (DSS)." (PMID 29312533, 2017). "Furthermore, a recent study reported that TLR4 activation seems to promote the development of colitis-associated cancer by enhancing Cox-2 expression and increasing epidermal growth factor receptor (EGFR) signalling." (PMID 20145615, 2010). "Thus, lack of ABCB1/MDR1-mediated signals appears to be closely intertwined with concordant suppression of the PTGS2 and EGFR signaling pathways in colitis-associated tumorigenesis, implying severe impairment of epithelial proliferation during inflammatory injury in-vivo." (PMID 28686677, 2017). "Strong EGFR activation in colonic macrophages was observed in human tissue microarrays (TMAs) during colitis and dysplastic changes." (PMID 40508145, 2025). "EPA supplementation effectively mitigates inflammation in acetic acid-induced rat colitis models by modulating the TGF-β/p-EGFR and NF-κB inflammatory pathways, restoring oxidant/antioxidant balance, and enhancing colonic barrier integrity." (PMID 40777179, 2025). "Considering the similar structure to EGF, we further examined if rSPINK4 rescued colitis by directly interacting with EGFR." (PMID 38997284, 2024). "Our results suggest SPINK4 as a receptor agonist of EGFR targeting the epithelium recovery, and participating in the colitis pathogenesis." (PMID 38997284, 2024). "Amphiregulin is known to contribute to intestinal epithelial regeneration, and IL-33 was shown to activate the amphiregulin-EGFR pathway to repair intestinal damage during DSS colitis." (PMID 38376154, 2024).
colitis (continued). "Our results suggest that SPINK4 participates in the regulation of intestinal regeneration and differentiation by directly influencing the EGFR pathway in colitis." (PMID 38997284, 2024). "Within SPINK4 deficiency in the epithelium, the expression of phosphorylated EGFR in colitis lesions decreased." (PMID 38997284, 2024). "The most studied ADAMs in IBD was Adam17, associated with EGFR and STAT3 signaling pathways crucial for the pathogenesis of colitis, high epithelial expression of which positively correlated with cell proliferation and goblet cell number in UC patients." (PMID 36901742, 2023). "Inhibiting EGFR signaling in mice recovering from colitis also promoted expression of pNF-κBs536 and pStat3y705 while the proliferative index was significantly lower, similar to that in Cldn2KO mice." (PMID 37815870, 2023). "In our study, we observed a very strong induction of EGF-pathway components during nematode infection, with even higher expressions of AREG and EGF, ligands for EGFR in mice infected with parasites and with induced colitis." (PMID 36836678, 2023). "Overall, our data indicated that the EGFR/CLDN2/Survivin axis and DDR signaling play a crucial role in colitis/inflammation-associated MH." (PMID 37815870, 2023). "Strong evidence indicates that p40 transactivation of EGFR in IECs contributes to ameliorating colitis in mice." (PMID 36159834, 2022). "Specifically, the role of EGFR in inflammatory pathologies of colon is well known, and the expression of EGFR has been found upregulate in experimental colitis and patients with UC, then regulates cytokines production and intestinal inflammation." (PMID 34177580, 2021). "In contrast, it is well known that epithelial EGFR mediates the wound healing process and protects against ulcerative injuries in IBD and colitis-associated tumorigenesis." (PMID 32461676, 2020). "Based on the growth studies, it is likely that EGFR activation by PGE2 is also the mechanism of the increased epithelial proliferation in the repair phase of DSS colitis." (PMID 33552081, 2020). "Inhibition of EGFR in Lingo2KO mice reversed the phenotype in models of colitis and helminth infection." (PMID 31562318, 2019). "Among these, the epidermal growth factor receptor (EGFR) and the downstream mitogen-activated protein kinase (MAPK) pathways are implicated in epithelial proliferation during DSS colitis and wound healing." (PMID 31002683, 2019). "A soluble protein, P40, secreted by the well-documented probiotic Lactobacillus rhamnosus GG (LGG) ameliorated DSS- and oxazolone-induced colitis through the activation of epidermal growth factor receptor (EGFR)." (PMID 29562943, 2018). "In conclusion, our data show that the effect of PACS-2 on ADAM17-mediated EGFR activation has negligible impact on DSS-induced colitis and the ApcMin model of cancer." (PMID 29312533, 2017). "Our in vivo studies showed that cetuximab, an anti-EGFR monoclonal antibody, effectively inhibited AOM/DSS-induced, colitis-associated tumorigenesis, downregulated M2-related markers, and decreased F4/80+/CD206+ macrophage populations." (PMID 27683110, 2016). "Lactobacillus rhamnosus GG was assessed for its ability to alleviate DSS-induced colitis in mice and activate epidermal growth factor receptor and Akt signaling in intestinal epithelial cells." (PMID 23990812, 2012). "This possibility will have to await testing in vivo to see the effect of EGFR/Her2 signaling inhibition in the context of a colitis-induced cancer model." (PMID 22988345, 2012). "In conclusion, we identified SPINK4 as not only a promising biomarker for the identification of IBD and estimation of the specific endoscopic status in colitis but also a target to ameliorate colitis by rebuilding GCs and the mucus layer via EGFR signaling and its downstream effectors." (PMID 38997284, 2024). "Thus, SPINK4 serves as a serologic biomarker of IBD and has therapeutic potential for colitis via intrinsic EGFR activation in intestinal homeostasis." (PMID 38997284, 2024).